FOXP3 (forkhead box P3)
Diseases named in the same sentence as FOXP3 in open-access papers (continued):
Sharing a sentence is not in itself a finding about the gene and the disease.
tuberculosis (continued). "IDO has been strongly implicated in immunity to tuberculosis, but usually in the context of regulatory T cells, surprising because our PCR data showed no significant Foxp3 signal." (PMID 29559116, 2018). "The pattern distribution of genotype at two position, −3279 A > C (rs3761548) and −924 A > G (rs2232365) on the promoter of FoxP3 gene was evaluated using polymerase chain reaction-single specific primer (PCR-SSP) method in 183 tuberculosis patients and 183 healthy control." (PMID 29020928, 2017). "These include the FoxP3 positive regulatory T cells and our findings validate their critical role in dampening the host effector T cell response during intracellular infections such as tuberculosis and leishmaniasis." (PMID 26751584, 2016). "Higher levels of FOXP3 mRNA have been observed in tuberculosis patients." (PMID 22509293, 2012). "The FoxP3+Treg cell activation which will assist to set up a new target for the involvement of TB immunotherapy molecules as part of the immune-escape mechanism to provide a theoretical basis is inhibited by M. tuberculosis." (PMID 31749827, 2019). "Lately, FoxP3 positive regulatory T cells (Tregs) have been characterized as one of the most potent hierarchic cell type suppressing effector T cell function with eventual regulation of immune response elicited by the host during intracellular infections such as tuberculosis and leishmaniasis." (PMID 26751584, 2016). "Our findings suggest that CD4+Foxp3+ cells play a time-dependent role in tuberculosis and highlight that CCR4 plays a critical role in the balance of IFN-γ-mediated inflammation by regulating the influx and function of CD4+Foxp3+ cells." (PMID 30584243, 2018). "In fact, among tuberculosis patients, enhanced levels of serum IL-10, in vitro cytokine production, increased expression of Treg cells (CD25+FOXP3+), and inhibition of the Th1 response were recently observed." (PMID 25992795, 2015). "In addition, the finding that the circulating Treg cells in the peripheral blood declined progressively by 2 months of anti-TB treatment is also in agreement with a recent report on CD4+CD25+FoxP3+ T cells in human tuberculosis." (PMID 23826366, 2013). "FOXP3 (Forkhead box P3) is a transcription factor present in certain regulatory (CD4+ CD25+) Treg cells, which regulates the immune response of the host during intracellular infections, such as tuberculosis and leishmaniasis." (PMID 34748560, 2021). "We addressed the role of CD4+Foxp3+ cells in tuberculosis pathogenesis, because this aspect has not been addressed during chronic infection." (PMID 30584243, 2018). "Our findings are translationally relevant, as CD4+Foxp3+ cells or CCR4 could be a target for immunotherapy, considering the heterogeneity of tuberculosis in immunocompetent adults." (PMID 30584243, 2018). "Studies suggest that the induction of regulatory T cell subpopulations (CD4+/CD25+/Foxp3+) may impair activation of the specific T cell repertoire (both CD4+ and CD8+) in active tuberculosis." (PMID 23824716, 2013). "Active tuberculosis in SCC increases the expression of CD3 (46.4±24.8 vs. 24.0±16.0, p<0.05), CXCR3 (35.1±16.4 vs. 19.2±13.3, p<0.01) and IP-10 (63.5±21.9 vs. 35.5±21.0, p<0.01), while expression of FOXP3 is decreased (3.5±0.5 vs. 13.3±3.7 p<0.05, p<0.05)." (PMID 22438899, 2012). "It has been previously reported that peripheral blood mononuclear cells (PBMCs) from patients with active tuberculosis (TB) had significantly higher proportions of CD4+CD25high T cells and FoxP3 mRNA expression levels than cells from healthy controls." (PMID 40771802, 2025). "IFN-γ stimulated responses are lowered in tuberculosis (TB), while expression of Suppressor of Cytokine Signaling (SOCS) molecules – 1 and 3 and CD4+CD25+FoxP3+T regulatory cells is increased." (PMID 23320781, 2013).
influenza (33 papers, 2008 to 2025). An acute viral infection of the respiratory tract, occurring in isolated cases, in epidemics, or in pandemics; it is caused by serologically different strains of viruses (influenzaviruses) designated A, B, and C, has a 3-day incubation period, and usually lasts for 3 to 10 days. "In particular, conserved decline in alveolar macrophage cells and expansion of immune suppressive Foxp3+ Tregs that parallel influenza susceptibility in naturally aged and LmnaDhe mice suggest these immune cell shifts play dominant roles impairing host defense with advancing age." (PMID 26248606, 2015). "FOXP3 knockout in tonsil T cells led to production of antibodies against a variety of autoantigens and increased the affinity of influenza-specific antibodies." (PMID 39806065, 2025). "Our results demonstrate that CD4+/CD25+FoxP3+ Tregs are involved in the pathogenesis of severe influenza and indicate the potential of the MEK-inhibitor zapnometinib to modulate CD4+/CD25+FoxP3+ Tregs." (PMID 38979428, 2024). "Treatment of aged mice with senolytics prior to influenza infection restored the differentiation of Th cells in those aged mice to a more youthful phenotype with fewer Th cells expressing FoxP3." (PMID 34962049, 2022). "To determine if more aged NP-specific CD4+ T cells exhibited regulatory T cell properties, we evaluated Foxp3 expression in young and aged influenza infected mice." (PMID 27109638, 2016). "In a mouse model for Influenza vaccinations the specific alterations of CD4+CD25+Foxp3+ regulatory T-cells (Tregs) in the immune modulation induced by orally supplied oligosaccharides containing scGOS/lcFOS/pAOS was assessed." (PMID 24073243, 2013). "No upregulation of PD-1, LAG-3, or TIM-3 was apparent on NP-specific memory CD8+ T cells either 2 or 6 months after influenza infection, and numbers of FoxP3+ regulatory T (Treg) cells were comparable." (PMID 22965681, 2012). "This incomplete depletion therefore raises the possibility of underestimation of the role Foxp3+ Treg cells play within influenza infection." (PMID 22125630, 2011). "We were unable to detect a greater increase in the number of Tregs (by Foxp3 staining) in the lymph nodes or spleens of influenza-infected IL-6−/− compared to WT mice." (PMID 18389078, 2008). "Therefore, to better understand the impact of CD4+/CD25+FoxP3+ Tregs on influenza disease progression, Tregs were induced by high dose IAV infection." (PMID 38979428, 2024). "Besides, Butyrate and propionate induce peripheral forkhead box protein P3 (FoxP3+) regulatory T cells, which promote influenza-specific T follicular helper." (PMID 36090099, 2022). "Finally, the fifth model we will discuss addressed the role of CD4+ FoxP3+ regulatory cells (Treg) during influenza infection by treating WT mice with anti-CD25 antibody (clone PC62) to deplete this subset prior to infection." (PMID 30641955, 2019). "Similar to the case in primary infection, lung tissue resident T cells, including Treg, CD4+Foxp3-, and CD8+ T cell subsets all expanded following secondary influenza infection." (PMID 36159872, 2022). "Strikingly in the murine model of influenza infection, CD8+ T cells are the largest subset of the IL-10-producing LAG3+CD49b+ T cells in the lungs (86%), followed by Foxp3− CD4+ T cells, while Foxp3+ CD4+ are a minority." (PMID 30510554, 2018). "In the present study, we demonstrated that CHS induced the presence of CD4+CD25+Foxp3+ Tregs, and this correlated with the downregulation of both Th1 and Th2 immune response stimulated by H5N1 influenza vaccination in mice." (PMID 24151582, 2013). "TGF‐beta levels, which drive FoxP3 expression, were also higher in the bronchoalveolar lavage of aged mice and blocking TGF‐beta reduced the percentage of FoxP3+ Th in aged lungs during influenza infection." (PMID 34962049, 2022).
influenza (continued). "The kinetics of tissue resident Foxp3-expressing Treg (TR-Treg) cells in the lungs during acute primary influenza infection is not as well characterized as the tissue resident memory CD8+ T cells." (PMID 36159872, 2022). "Profiling of multiple well-established Treg cell suppressive markers, including Foxp3, showed no significant age-related difference during the recovery phase of influenza infection." (PMID 33600379, 2021). "Finally, a protocol was established to investigate the extent to which FoxP3+ regulatory CD4 T cells impact the outcome of primary and heterosubtypic influenza infection." (PMID 30641955, 2019). "In addition to virus-specific CD4+ T cells and CD8+ T cells responses, FoxP3+ CD4+ regulatory T cells (Tregs) and T helper 17 cells (Th17) are also induced during influenza infection." (PMID 26407325, 2015). "For influenza-specific CD8+ T cells, we utilized an MHC class I tetramer specific for H-2Db-resricted epitope of the influenza nucleoprotein (NP, DbNP366-74) of PR/8, and CD4+ Tregs were identified by expression of the transcription factor Foxp3." (PMID 24844920, 2014). "Influenza infection stimulates protective host immune responses but paradoxically enhances lung indoleamine 2,3 dioxygenase (IDO) activity, an enzyme that suppresses helper/effector T cells and activates Foxp3-lineage regulatory CD4 T cells (Tregs)." (PMID 23785507, 2013). "During the first week post-vaccination, TREG cells (CD3+CD4+FOXP3+) harbored the highest predictive value (AUC approximately 0.9) with respect to the other cell compartments, thus substantiating the hypothesized role of TREG cells as a driving force that determine influenza vaccine responsiveness." (PMID 36371426, 2022). "We found that IL-21hi cells exhibited the highest expression levels of Il21, Bcl6, and Cxcr5 but not Foxp3, compared with other cell populations, suggesting that TRH cells but not regulatory T cells express IL-21 in the lung after influenza infection." (PMID 38345472, 2024). "In influenza infection, ICOS stimulation is needed to maintain FOXP3 expression in the absence of IL-2." (PMID 36672230, 2023). "To further elucidate whether engraftment was influenced by the inflammatory microenvironment of the lung, we harvested adoptively transferred Foxp3-GFP+tdTomato+ cells from the spleens and lungs of Foxp3GFP-DTR recipients of Uhrf1+/+ or Uhrf1fl/fl iTregs that received DTx but not influenza." (PMID 40956625, 2025).
lymphopenia (33 papers, 2010 to 2025). Reduction in the number of lymphocytes. "As a control, we assessed the transcriptional effects of Foxp3 degradation upon short-term transfers of the same Treg cell mixture into T cell-deficient mice, which afford lymphopenia-induced Treg cell proliferation in a minimal inflammatory setting." (PMID 41062655, 2025). "For example, peripheral interconversion between Th17 cells and Tregs has been observed in the presence of IL-6 and TGF-β1, and a loss of Foxp3 expression along with regulatory functions has been observed in the context of lymphopenia." (PMID 33289628, 2020). "These Foxp3+ Treg expressed nTreg marker Helios, indicating that the relative enrichment of Tregs in the periphery of Rptf/f-Foxn1Cre mice was likely caused by lymphopenia-induce proliferation because Treg expansion is superior to Teff under such condition." (PMID 26889835, 2016). "We next compared lymphopenia-induced immune responses of MP versus naïve cells by separately transferring MP and naïve Foxp3− CD4+ T lymphocytes into Rag2−/− mice." (PMID 39630890, 2024). "In this study, we demonstrate that conditional ablation of Ripk1 in conventional T cells (Ripk1ΔCD4) causes peripheral T cell lymphopenia, as witnessed by a profound loss of naive CD4+, naive CD8+, and FoxP3+ regulatory T cells." (PMID 38734851, 2024). "Altogether, our results in Ripk1ΔCD4 mice show the essential role of RIPK1 scaffold function in the homeostasis of naive CD4+ and CD8+ T cells and FoxP3+ Treg cells and in preventing T cell lymphopenia." (PMID 38734851, 2024). "Repopulation of FOXP3+ T regulatory cells after lymphopenia normally occurred, suggesting escape of skin-reactive conventional T cells from control by regulatory T cells." (PMID 38576231, 2024). "Collectively, these observations suggest that Foxp3+ Tregs can lose Foxp3 expression and undergo lineage reprogramming in response to certain extrinsic cues such as lymphopenia and inflammation." (PMID 31608056, 2019). "By contrast, a Tmem population (precisely, Foxp3−CD44hiCD73hiFR4hi T cells) efficiently express Foxp3 during lymphopenia." (PMID 30061879, 2018). "Along with a CD4+ T-cell lymphopenia, FOXP3+ T-cell numbers are reduced in the blood of patients with PHTS, but we observed normal frequency of Treg cells in the blood and colon." (PMID 27477328, 2017). "This resulted in moderate lymphopenia as reflected in a reduced number of CD4+FoxP3− Tcons in the spleen." (PMID 26973650, 2016). "It further provides new insights into the regulation of TGF-β-induced FoxP3 expression as well as lymphopenia-induced expansion of T cells by Tpl2." (PMID 25781948, 2015). "Based on the results of our adoptive transfer experiments, we speculate that one factor may be that a strict requirement for Foxp3 exists in neonates, when the first cohorts of newly generated T cells undergo a phase of lymphopenia-driven activation." (PMID 40478934, 2025). "There is, however, mounting evidence in mouse models indicating that Treg cells can, under inflammatory conditions such as lymphopenia or chronic infections, lose their Foxp3 expression and suppressive function and differentiate into Teff-like cells with inflammatory potential." (PMID 31379810, 2019). "Furthermore, Ripk1ΔCD4Casp8 ΔCD4 and Ripk1ΔCD4Tnfr1−/− double-knockout mice rescued the peripheral T cell lymphopenia, revealing that RIPK1-deficient naive CD4+ and CD8+ cells and FoxP3+ regulatory T cells specifically die from TNF- and caspase-8-mediated apoptosis in vivo." (PMID 38734851, 2024). "FoxP3+ T cells (putative regulatory T cells) decreased with lymphopenia as did CD8+ T cells (data not shown)." (PMID 40612959, 2025).
lymphopenia (continued). "Later, as physiological lymphopenia disappears and homeostatic proliferation declines, the proportion of non-dividing T cells increases, and resting, non-dividing Foxp3+Helios- with naïve CD44low would appear in the periphery." (PMID 21918685, 2011). "Within the adaptive immune compartment, global T and B cell lymphopenia predominated in critically ill patients, with the remaining T cell pool enriched with PD-1+ CD4+ and CD8+ T cell clusters (CD4-2, CD4-3 and CD8-6) and regulatory T (Treg) cell (CD4+CD25+FoxP3+, CD4-4) clusters." (PMID 36894652, 2023).
bladder cancer (32 papers, 2011 to 2025). "The association between bladder cancer risk and the distribution of SNPs in FOXP3 among patients and controls." (PMID 39935826, 2025). "The metaanalysis from 2 larger published datasets of bladder cancer showed Foxp3 expression is significantly associated with GLUT−4, −9 and VEGF-A, -B, -D mRNA expression, rather than HIF-1α mRNA expression." (PMID 27557492, 2016). "Moreover, high FOXP3/CD8 ratio is associated with poor prognosis of patients with bladder cancer." (PMID 32733809, 2020). "However, the underlying biological function of Foxp3 protein remains unclear in human bladder cancer." (PMID 27557492, 2016). "However, the relationship of Foxp3 polymorphism and bladder cancer (BC) remain unclear." (PMID 39935826, 2025). "Using in vitro and in vivo human and murine models, we showed that FOXP3 can influence bladder cancer EMT as well as promote cancer metastases." (PMID 39099201, 2024). "We have previously shown that bladder cancer expression of FOXP3 predominates as an alternatively spliced form, FOXP3Δ3, and negatively correlates with patient outcomes." (PMID 39099201, 2024). "In bladder cancer, we defined a novel mechanism whereby FOXP3 mediates the activation of the immune checkpoint PD-L1 by the cytokine IFNγ." (PMID 39099201, 2024). "We previously have shown that bladder cancers predominantly express the FOXP3Δ3 isoform over the full-length FOXP3, including in HT1376 cells." (PMID 39099201, 2024). "To confirm our findings in primary tumors, we examined the correlation of FOXP3 and PD-L1 in six high-grade bladder cancer specimens and showed colocalization of FOXP3 and PD-L1 expression." (PMID 39099201, 2024). "MB49 cells have a low basal expression of FOXP3 and PD-L1, whereas stimulation of MB49 cells by IFNγ leads to upregulation of both FOXP3 and PD-L1, consistent with our findings in human bladder cancer cell lines." (PMID 39099201, 2024). "In summary, we describe the role of FOXP3 in bladder cancer cells that promotes a more aggressive phenotype both histologically as well as functionally." (PMID 39099201, 2024). "In the present study, we investigated the relevance of CD3+, CD8 +, CD45RO +, and FOXP3 + TILs to the prognosis and survival of patients with bladder cancer and the disease's clinical-pathological parameters." (PMID 36038861, 2022). "To explore the regulation of α-TIGIT in Treg cells, we analyzed the expression of CD25, TIGIT, and FOXP3 in murine bladder cancer tissues." (PMID 35069212, 2021). "Bladder cancer is infiltrated by FOXP3+ T-cells (Tregs) with production of TH1 inhibitory cytokines." (PMID 32733809, 2020). "In term of bladder cancer, Foxp3 expression can be detected in tumor cell nuclei or cytoplasm and a positive Foxp3 expression (either 10 cytoplasmic, 3 nuclear, or 4 mixed) is an unfavorable indicator for disease progression and overall survival." (PMID 27557492, 2016). "This reverse post-translational regulation of HIF-1α protein by Foxp3 provides a new potential target for developing new therapeutic strategy for bladder cancer." (PMID 27557492, 2016). "In the present study, we evaluated tumor-infiltrating lymphocytes (TILs) and blood regulatory T lymphocyte (Tregs, CD4+/CD25+/FoxP3+) expression in bladder cancer patients." (PMID 26927070, 2016). "In this study, we unveil a reverse regulatory mechanism contributing to bladder cancer progression; Foxp3 expression attenuates HIF-1α degradation." (PMID 27557492, 2016). "FOXP3.mod hi and FOXP3.mod lo bladder carcinoma samples showed less pronounced copy number differences than the other tumor types, but still had an excess of significant genes at chromosome 17q1 when compared with randomly partitioned tumors." (PMID 26398410, 2015). "These points suggest that IFI27 may be involved in regulating FOXP3 expression in bladder cancer, which requires further studies in the future." (PMID 39668835, 2024).